TTR (transthyretin)
Diseases named in the same sentence as TTR in open-access papers (continued):
Sharing a sentence is not in itself a finding about the gene and the disease.
myopia (9 papers, 2008 to 2025). "The functional impairment observed in the macular region of pathological myopia is associated with elevated TTR expression." (PMID 40837568, 2025). "TTR may serve as both a biomarker and a pathogenic factor in myopia progression, offering potential targets for future therapeutic interventions." (PMID 40605078, 2025). "Our current results suggest that TTR may also be associated with myopia." (PMID 18334949, 2008). "Serum analyses further demonstrate that TTR levels, a key TH transport protein, are significantly elevated in patients with high myopia and correlate with increased axial length and decreased visual acuity." (PMID 40605078, 2025). "Elevated vitreous TTR concentrations have also been detected in patients with high myopia complicated by macular detachment or macular holes." (PMID 40605078, 2025). "Two of these myopia-specific exosomal proteins, TTR and HPX have been found in previous myopia associated research." (PMID 33850473, 2021). "Higher TTR levels have also been detected in the vitreous of myopia, macular detachment, and macular hole patients." (PMID 33850473, 2021). "One of the later identified proteins using ESI-MS/MS, was TTR, which was significantly increased in patients with myopia." (PMID 18682810, 2008). "In addition, the TTR concentration in vitreous samples from high myopia with ocular pathology was significantly higher than that in the other two groups, and this trend was consistent with that observed in serum samples." (PMID 39597899, 2024). "Our previous work has demonstrated that higher vitreous TTR content of high myopia patient might help to prevent the progression of DR." (PMID 31847264, 2019). "Regarding some clinical investigations of ocular diseases, myopia is suggested to prevent patients from suffering DR; therefore, in our previous work, we studied the relationship between the higher vitreous TTR level of high myopia patients and the DR protection phenomenon." (PMID 31847264, 2019). "While there may be complex interactions between thyroid dysfunction and pathological myopia, and TTR may serve as a molecular bridge between these conditions, this does not necessarily indicate a direct genetic link, particularly in relation to RHO gene mutations." (PMID 40837568, 2025). "Previous studies have demonstrated that fundus alterations in pathological myopia are associated with increased levels of transthyroxin (TTR), whereas TTR levels are significantly reduced in the fundi of individuals with high myopia but without significant pathological changes." (PMID 40837568, 2025). "In addition, TTR has also been found in the AH of high myopia patients." (PMID 33850473, 2021).
type 1 diabetes (9 papers, 2006 to 2025). "Low levels of plasma TTR have been found in patients affected by diabetes type I [4.4 μmol/L (24 mg/dL) compared to 5.3 μmol/L(29 mg/dL) in normal subjects], reinforcing the hypothesis that TTR may be associated with glucose homeostasis." (PMID 36009453, 2022). "In patients with type 1 diabetes, serum tetrameric TTR concentrations are lower and monomeric TTR concentrations are higher than in healthy controls." (PMID 40717228, 2025). "Taken together, the conversion of tetrameric TTR to its monomeric form has been proposed to mediate the development of β-cell failure/destruction in type 1 diabetes." (PMID 40717228, 2025). "TTR was also detected at lower levels in the individuals with type 1 diabetes, and, of further relevance to the islet cells, the homo-tetramer of TTR has been reported in relation to the preservation beta cell integrity and secretion." (PMID 37537394, 2023). "Patients with type 1 diabetes had lower serum levels of transthyretin than healthy controls." (PMID 19077222, 2008). "Furthermore, transthyretin has been shown to play a role in type 1 diabetes." (PMID 19077222, 2008). "In another study the levels of TTR in patients with non-insulin dependent diabetes were not affected and in inflammatory states TTR has been shown to decrease." (PMID 17163994, 2006).
vitamin A deficiency (9 papers, 2011 to 2025). Deficiency of vitamin A due to malnutrition, malabsorption, or dietary lack. "A simple decision rule {(−15.277 × [RBP, μmol/L] - 7.013 × [Transthyretin, μmol/L] + 0.367 × [C-reactive protein, mg/L] + 24.714) > 0.496} yielded prevalence estimates of vitamin A deficiency that is unbiased by diagnostic error." (PMID 25856672, 2015). "TTR is closely associated with the vitamin A–RBP complex, and the RBP/TTR ratio can be used for the indirect assessment of vitamin A status; a decreased ratio reportedly signifies a vitamin A deficiency." (PMID 21156399, 2011). "The RBP/TTR molar ration provides an indirect way to indicate marginal vitamin A deficiency." (PMID 23844025, 2013). "Proxy markers for vitamin A deficiency were serum concentrations of retinol binding protein (RBP), transthyretin, retinol measured by fluorometry and RBP:transthyretin molar ratio." (PMID 25856672, 2015). "Logistic regression resulted in a model of vitamin A deficiency dependent on RBP, transthyretin and C-reactive protein and a linear predictor of (−15.277 × [RBPμmol/L] - 7.013 × [Transthyretinμmol/L] + 0.367 × [C-reactive proteinmg/L] + 24.714)." (PMID 25856672, 2015). "Only 10% had inflammation; their exclusion from analysis led to similar estimates for concentrations of retinol (whether HPLC or fluorometry), RBP, transthyretin, RBP:transthyretin molar ratio and prevalence of vitamin A deficiency." (PMID 25856672, 2015). "When used in combination, RBP and transthyretin were better at discriminating between children with and without vitamin A deficiency than when transthyretin was used alone (AUC: 0.98 versus 0.96; P = 0.01) or when RBP was used alone (AUC: 0.98 versus 0.93; P = 0.001)." (PMID 25856672, 2015). "The combination of transthyretin, RBP and C-reactive protein concentrations could eventually replace retinol concentration by HPLC in resource-poor settings as the preferred method to assess the population burden of vitamin A deficiency." (PMID 25856672, 2015). "Serum concentrations of transthyretin and RBP, when used alone, performed well in discriminating between children with and without vitamin A deficiency." (PMID 25856672, 2015).
cardiac hypertrophy (8 papers, 2018 to 2025). "First, PYP scans are able to detect TTR fibrils in the heart prior to the onset of cardiac hypertrophy and electrophysiological changes." (PMID 33595871, 2021). "Similarly to mATTR, native TTR proteins can lead to the cardiac infiltration and deposits of TTR amyloid fibrils and subsequently to stiffness, tissue fibrosis and organ dysfunction in the setting of cardiac hypertrophy." (PMID 39963604, 2025).
coronary artery disease (8 papers, 2019 to 2025). "Circulatory transthyretin, ALT and AST were associated with low muscle mass in people with coronary heart disease." (PMID 36891188, 2023). "Low levels of transthyretin, an important transport protein of the acute phase, were confirmed in all patients with coronary heart disease." (PMID 34948066, 2021). "The authors suggested that a lower level of transthyretin allows predicting the severity of the disease and can serve as an important marker for the screening of coronary heart disease." (PMID 34948066, 2021). "In addition, TTR levels have been shown to be lower in the serum and peripheral blood mononuclear cells isolated from patients with coronary artery disease compared with healthy controls." (PMID 40717228, 2025). "This study aimed to assess circulatory biomarkers related to these mechanisms [albumin, transthyretin, alanine aminotransferase (ALT), aspartate aminotransferase (AST), and C-terminal agrin fragment] and their relationship with muscle mass in people with coronary heart disease." (PMID 36891188, 2023).
left ventricular hypertrophy (8 papers, 2021 to 2025). Enlargement of the LEFT VENTRICLE of the heart. "Sixteen TTR-mutation carriers (mean age 51 ± 9 years, 6 males, 7 with Val30Met and 9 with Phe64Leu mutation) without left ventricular hypertrophy were studied." (PMID 39639351, 2024).
pancreatic cancer (8 papers, 2013 to 2025). "Our previous study showed that TTR is overabundant in pancreatic juice from patients with pancreatic cancer and CP." (PMID 35741777, 2022). "Compared with the control group, patients with pancreatic cancer showed at least 2-fold lower serum apolipoprotein A-II, transthyretin, and apolipoprotein A-I levels." (PMID 34454509, 2021). "Down-regulated apolipoprotein A-II, transthyretin, and apolipoprotein A-I were described as potential markers in pancreatic cancer." (PMID 23401773, 2013). "In a previous study, TTR was shown to be upregulated by two-fold in pancreatic cancer, thus, it was concluded that TTR may be used as a novel tumor marker." (PMID 24940434, 2014). "In pancreatic cancer, this has been recently studied for the protein transthyretin (TTR), an islet cell protein that is elevated in pancreatic juice from pancreatic cancer patients through destruction of islet cell architecture in the presence of invasive cancer." (PMID 24007603, 2013). "Among them, positive (i.e., serum amyloid A, ceruloplasmin, complement factors, haptoglobin) and negative acute-phase reactants (i.e., transthyretin, transferrin) were differentially expressed in sera from ovary, lung, liver, and pancreatic cancer patients." (PMID 23401773, 2013).
rheumatoid arthritis (8 papers, 2015 to 2025). A chronic, systemic autoimmune disorder characterized by inflammation in the synovial membranes and articular surfaces. "Additionally, increased serum levels of transthyretin were associated with the severity of rheumatoid arthritis, suggesting a role in disease pathogenesis." (PMID 27878954, 2017). "Increased glycated TTR and RAGE protein levels have been found in patients suffering from rheumatoid arthritis, in association with increased levels of the pro-inflammatory cytokines IL-1β, IL-6, and TNF-α, suggesting a role of TTR/RAGE in this inflammatory disorder." (PMID 39766257, 2024). "Similarly, reduced transthyretin levels were determined in patients with rheumatoid arthritis during exacerbation of their symptoms." (PMID 37571416, 2023). "TTR downregulation has been detected in the plasma of rheumatoid arthritis (RA) patients." (PMID 34359938, 2021). "Rheumatic and osteoarticular diseases, which encompass inflammatory and degenerative conditions such as rheumatoid arthritis (RA), osteoarthritis, and osteoporosis, may be impacted by modulation of TTR." (PMID 40717228, 2025).
osteoarthritis (7 papers, 2017 to 2022). A noninflammatory degenerative joint disease occurring chiefly in older persons, characterized by degeneration of the articular cartilage, hypertrophy of bone at the margins and changes in the synovial membrane. "The literature has also shown some relief effect of GPC on senescence, transthyretin deposition, and osteoarthritis in aged mice." (PMID 35208251, 2022). "Four different forms of TTR were detected in mass spectra of sera from patients with RA, early RA, osteoarthritis (OA), and healthy control group." (PMID 34359938, 2021). "This hypothesis was supported by a mouse model of osteoarthritis, where it was shown that the overexpression of TTR worsened the progression of the disease." (PMID 33274477, 2021). "In knee joints of 12 out of 12 osteoarthritis patients, as well as 7 out of 12 aged individuals without osteoarthritis, amyloid was present in menisci, articular cartilage, and synovial membranes, mostly of TTR and Apo-AI origin." (PMID 32604774, 2020).
anemia (6 papers, 2016 to 2025). A reduction in the number of red blood cells, the amount of hemoglobin, and/or the volume of packed red blood cells. "Our results show that HDF patients have decreased TTR levels and a reduced incidence of anaemia and rhEPO requirements." (PMID 32994444, 2020). "Among women we found correlations between anemia and several markers of inflammation, such as decreased transthyretin (<0.23 g/L), increased ferritin (>204 μg/L), and increased CRP (≥10 mg/L)." (PMID 27912734, 2016). "Thus, TTR could be a critical actor for anaemia in ESRD patients and could also be a novel biomarker for haemodialysis adequacy." (PMID 32994444, 2020). "Thus, our suggested mechanism for anaemia in ESRD patients is that an increased level of TTR could induce TTR aggregates, inhibiting transferrin endocytosis, this, in turn, decreases intracellular iron, reducing erythropoiesis and leading to anaemia." (PMID 32994444, 2020). "Thus, transthyretin could be a critical actor for anaemia in ESRD patients and a novel player for haemodialysis adequacy." (PMID 32994444, 2020). "Anemia has not been found to predict or to be correlated with the occurrence of relapse of disease, but rather to have an influence on the TTR." (PMID 38337488, 2024). "Among men with anemia, there was a correlation with increased CRP, but not with increased ferritin (>275 μg/L) or transthyretin (<0.23 g/L)." (PMID 27912734, 2016).
gastric cancer (6 papers, 2020 to 2025). A primary or metastatic malignant neoplasm involving the stomach. "In addition, the prognostic value of TTR is also notable with respect to mortality in several forms of malignancy, for example in liver cancer and gastric cancer, in which low levels of TTR are associated with poor prognosis and increased mortality." (PMID 40717228, 2025).
glioma (6 papers, 2011 to 2025). A benign or malignant brain and spinal cord tumor that arises from glial cells (astrocytes, oligodendrocytes, ependymal cells). "Bioinformatics analysis using TIMER2.0 and GEPIA 2.0 revealed positive correlations between CLU expression and several genes (BAX, BCL2L1, PRNP, HSPA5, LRP2, TTR, all p < 0.05), suggesting synergistic or antagonistic interactions during glioma development." (PMID 40606578, 2025). "Transthyretin was one of several serum proteins that were elevated in pateints with suspected gliomas undergoing surgery." (PMID 23185417, 2012). "It seems unlikely that the changes in CSF transthyretin levels in this study represent release from these small nests and microtumors at this early stage of glioma development, but confirmation of this is worthy of more study." (PMID 23185417, 2012). "Although there was no direct evidence of an association between TTR and LGG, the gene might be involved in the prognostic change of IDH mutation because TTR has a role in the transport of thyroid hormone related to the progression of glioma tumor cells." (PMID 41007824, 2025).
Hyperglycemia (6 papers, 2019 to 2022). An increased concentration of glucose in the blood. "In this study, through RNA-sequencing, the basic transcriptome characteristics of hRECs underlying hyperglycemia and TTR with high glucose conditions were first determined." (PMID 31615521, 2019). "TTR can interact with hnRNPA2B1 to form a TTR-hnRNPA2B1 complex, which plays a critical role in TTR’s anti-angiogenesis function in hyperglycemia via the STAT4/miR-223e3p/FBXW7 signaling pathway." (PMID 36277184, 2022). "In another study, to investigate how TTR affects the development of new vessels in DR, human retinal microvascular endothelial cells (hRECs) were cultured with TTR in natural and simulated DR environments (hyperglycemia and hypoxia)." (PMID 34429155, 2021).
lumbar spinal stenosis (6 papers, 2017 to 2025). A spinal stenosis that involves the lumbar region of vertebral column. "Several studies report an association between lumbar spinal stenosis and TTR amyloid deposits within the ligamentum flavum." (PMID 33419417, 2021). "One mutation was identified in a gene that could be associated with lumbosacral stenosis – transthyretin (protein associated with human lumbar spinal stenosis)." (PMID 29085643, 2017).
melanoma (6 papers, 2013 to 2023). A malignant, usually aggressive tumor composed of atypical, neoplastic melanocytes. "In addition, VIM, TTR, and TYR genes were used to evaluate the diagnosis of melanoma, which suggested VIM and TYR involved in pigment synthesis, and the mechanism of action needs further study." (PMID 37402463, 2023). "Moreover, TTR is stimulated LLC and B16 melanoma cell proliferation." (PMID 34066808, 2021). "At the same time, a reduction in TTR was observed at both centres, thus confirming that a reduction in NNE was obtained without an increase in missed early melanomas, as supposed from previous reports." (PMID 34884250, 2021).
normal pressure hydrocephalus (6 papers, 2014 to 2026). A form of compensated hydrocephalus characterized clinically by a slowly progressive gait disorder (see gait disorders, neurologic), progressive intellectual decline, and urinary incontinence. "The present work aims to examine the expression and distribution of TTR in the SCO to define if the functional activity of SCO improves or early regress associated with the type of hydrocephalus." (PMID 36553409, 2022). "Clearance rates of transthyretin are ∼10 fold slower in normal pressure hydrocephalus compared with controls, suggesting impaired CSF protein clearance." (PMID 41737284, 2026). "In one of the communicating cases of hydrocephalus, the TTR immunoreactivity was found in the perinuclear and apical cytoplasm of many ependymal cells at the retro-commissural area of SCO." (PMID 36553409, 2022). "In the fetus with non-communicating hydrocephalus, TTR immunoreactivity was detected in the apical and perinuclear zone of the ependymocytes and the cytoplasm of some hypendymocytes of the pre, sub, and retro-commissural regions from the SCO." (PMID 36553409, 2022). "NG2 antigen, TTR, and PI and PS molecular species of lipids have been found as possible biomarkers for the pathogenesis of hydrocephalus." (PMID 34215285, 2021). "Notably, the application of the Stable Isotope Labelling Kinetic (SILK) method in patients with normal pressure hydrocephalus has been pivotal in monitoring changes in the dynamics of CSF biomarkers, such as Transthyretin (TTR)." (PMID 38773599, 2024). "However, in communicating hydrocephalus cases, TTR-positive cells are scarce in the pre-commissural or rostral part of the SCO." (PMID 36553409, 2022). "In any case, TTR can be suggested as a biomarker of parenchymal changes in hydrocephalus." (PMID 34215285, 2021). "The human SCO at the gestational ages analyzed showed expression at TTR, and the intensity of the reaction was observed at 20 weeks of gestation in the fetus without hydrocephalus and the obstructive case, which coincides with the moments of significant development of the human SCO." (PMID 36553409, 2022). "TTR expression was found in the apical pole, around the nucleus, and in the perinuclear cytoplasm of several hypendymal cells in the precommissural and retrocommissural areas of the control cases and non-communicant hydrocephalus." (PMID 36553409, 2022).
sarcopenia (6 papers, 2018 to 2026). Progressive decline in muscle mass due to aging which results in decreased functional capacity of muscles. "It is known that, during the inflammatory process, the synthesis of acute phase proteins such as C-Reactive Protein (CRP) predominates, consequently reducing the synthesis of transthyretin (TTR), which is associated with sarcopenia." (PMID 39519615, 2024). "In hospitalised people with CHD, albumin and transthyretin levels are lower in the presence of sarcopenia (as defined by the Asian Working Group for Sarcopenia) compared to those defined as non-sarcopenic." (PMID 36891188, 2023). "In addition, future studies may investigate the use of novel serum biomarkers such as plasma transthyretin (TTR), which has been shown to be a surrogate marker of changes in lean body mass, as possible alternatives to imaging modalities for the diagnosis of sarcopenia." (PMID 29642478, 2018).